RRAGA (Ras related GTP binding A)
Description:
Guanine nucleotide-binding protein that plays a crucial role in the cellular response to amino acid availability through regulation of the mTORC1 signaling cascade. Forms heterodimeric Rag complexes with RagC/RRAGC or RagD/RRAGD and cycles between an inactive GDP-bound and an active GTP-bound form: RagA/RRAGA is in its active form when GTP-bound RagA/RRAGA forms a complex with GDP-bound RagC/RRAGC (or RagD/RRAGD) and in an inactive form when GDP-bound RagA/RRAGA heterodimerizes with GTP-bound RagC/RRAGC (or RagD/RRAGD). In its GTP-bound active form, promotes the recruitment of mTORC1 to the lysosomes and its subsequent activation by the GTPase RHEB. Involved in the RCC1/Ran-GTPase pathway. May play a direct role in a TNF signaling pathway leading to induction of cell death. (Microbial infection) May alternatively act as a cellular target for adenovirus E3-14.7K, an inhibitor of TNF functions, thereby affecting cell death.
Synonyms: RagA; FIP-1; FIP1
Tractability: Small molecule: a structure with a bound ligand is known. PROTAC: UniProt records ubiquitination sites on it; ubiquitination databases record sites on it; its protein half-life has been measured.
Gene: Protein-coding gene on chromosome 9 (19,049,427 to 19,051,025, forward strand). Ensembl gene ENSG00000155876.
Subcellular location: Cytoplasm; Nucleus; Lysosome membrane
Subcellular location (Human Protein Atlas): Golgi apparatus; Vesicles
Pathways (Reactome):
Signal Transduction: Energy dependent regulation of mTOR by LKB1-AMPK; MTOR signalling; Regulation of PTEN gene transcription; mTORC1-mediated signalling
Autophagy: Macroautophagy
Cellular responses to stimuli: Amino acids regulate mTORC1
Metabolism of proteins: E3 ubiquitin ligases ubiquitinate target proteins
Gene Ontology:
Molecular function: GTP binding; GTPase activity; phosphoprotein binding; protein binding; protein heterodimerization activity; protein homodimerization activity; protein-membrane adaptor activity; ubiquitin protein ligase binding
Biological process: cellular response to amino acid starvation; cellular response to amino acid stimulus; cellular response to nutrient levels; intracellular protein localization; intracellular signal transduction; negative regulation of autophagy; positive regulation of TORC1 signaling; protein localization to lysosome; protein localization to membrane; tumor necrosis factor-mediated signaling pathway; cellular response to starvation; positive regulation of TOR signaling; glucose homeostasis
Cellular component: cytoplasm; FNIP-folliculin RagC/D GAP; GATOR1 complex; Gtr1-Gtr2 GTPase complex; lysosomal membrane; lysosome; nucleoplasm; nucleus; cytosol
Genetic constraint (gnomAD): Loss-of-function variants: 11 observed, 21.77 expected, observed/expected ratio (o/e) 0.51, 90% interval 0.32 to 0.84. The upper end of that interval is the gene's LOEUF score, 0.84, which puts it in group 3 of 6, group 1 being the genes least tolerant of losing a copy. Missense variants: 214 observed, 430.37 expected, observed/expected ratio (o/e) 0.5, 90% interval 0.44 to 0.56. Synonymous variants: 184 observed, 169.41 expected, observed/expected ratio (o/e) 1.09, 90% interval 0.96 to 1.23.
Homologues: Orthologues: chimpanzee RRAGA (100% identical), dog RRAGA (100% identical), guinea pig RRAGA (100% identical), macaque RRAGA (100% identical), mouse Rraga (100% identical), pig RRAGA (100% identical), rabbit RRAGA (100% identical), rat Rraga (100% identical), tropical clawed frog rraga (98% identical), zebrafish rraga (88% identical), Drosophila melanogaster RagA-B (77% identical), Caenorhabditis elegans raga-1 (64% identical). Paralogues in human: RRAGB (98% identical), RRAGC (27% identical), RRAGD (26% identical).
Diseases named in the same sentence as RRAGA in open-access papers:
RRAGA is named in the same sentence as 34 diseases in open-access papers, as found by Europe PMC text mining. Sharing a sentence is not in itself a finding about the gene and the disease. The quoted sentences say what the papers report.
autosomal dominant cataract (3 papers, 2016 to 2023). A syndromic cataract that has autosomal dominant inheritance. "Mutations in RRAGA (Ras related GTP binding A), the gene encoding the RagA GTPase that regulates mTORC1, are associated with autosomal dominant cataracts." (PMID 37034386, 2023). "Mutations in RRAGA as a critical regulator of mTORC1 (mechanistic rapamycin complex 1) are closely associated with autosomal dominant cataracts." (PMID 35892841, 2022). "We next screened RRAGA for possible mutations in probands of 22 families with autosomal dominant cataracts, and 142 unrelated patients with congenital or juvenile-onset cataracts." (PMID 27294265, 2016). "In summary, our study identifies mutations in the Rag GTPase RRAGA, in the mTORC1 pathway, to be associated with autosomal dominant cataracts, and provides supporting functional evidence." (PMID 27294265, 2016). "Herein, we report that mutations in the RagA GTPase (RRAGA), a key regulator of the mechanistic rapamycin complex 1 (mTORC1), are associated with autosomal dominant cataracts." (PMID 27294265, 2016). "Our findings thus indicate that the RRAGA mutations are associated with autosomal dominant cataracts through disruption of the mTORC1 pathway, a substantial modulator of ageing and age-related human diseases." (PMID 27294265, 2016). "Our results thus show that RRAGA, which encodes the RagA GTPase, is a novel gene associated with autosomal dominant cataracts, and implicate a novel mechanism involving the mTORC1 pathway that is different from our prior knowledge of cataracts." (PMID 27294265, 2016). "The discovery of association between mTORC1 pathway gene RRAGA and autosomal dominant cataracts has important implications for our understanding of cataract disease and ageing." (PMID 27294265, 2016). "In the current study, the conserved Leu60 residue mutated in juvenile-onset cataract patients is in the switch II region responsible for RRAGA activation, and is spatially close to the Mg2+ binding site." (PMID 27294265, 2016). "Therefore, RRAGA mutations probably cause autosomal dominant cataracts by disrupting autophagy." (PMID 27294265, 2016). "Taken together, these findings show involvement of RRAGA as a mechanism for autosomal dominant cataracts." (PMID 27294265, 2016). "In the current study, whole exome sequencing has led to the identification of the RagA GTPase (RRAGA) gene for cataracts and we proceeded to study properties of the RRAGA protein." (PMID 27294265, 2016). "This study gives important new insight into the roles of RRAGA and mTROC1 signaling in the etiology of cataracts." (PMID 27294265, 2016). "Notably, RRAGA p.Leu60Arg was observed in an unrelated patient with juvenile-onset anterior and posterior subcapsular cataracts (CC38)." (PMID 27294265, 2016).
breast carcinoma (2 papers, 2023 to 2025). "For example, CpGs exhibiting higher methylation levels in female cetaceans were linked to genes such as the mTOR-related RRAGA on chromosome 9 (cg04565674, Meta P = 1.0 × 10–159) and the breast cancer-related gene BCAR3 on chromosome 1 (cg06678289, Meta P = 4.6 × 10–36), among others." (PMID 39900928, 2025).
Hypoglycemia (2 papers, 2017 to 2020). A decreased concentration of glucose in the blood. "While HAUS6 and its nearby genes RRAGA and PLIN2 have various cancers (including PrCa) as associated diseases in Open Targets Genetics, one or more of them are related to metabolism phenotype, abnormal gluconeogenesis and hypoglycemia in mice." (PMID 33290408, 2020).
Hypertension (1 paper, 2025). The presence of chronic increased pressure in the systemic arterial system. "Among tissues linked to hypertension, PPP1R14D (Z = 3.12) and AMN (Z = 2.12) show maximal expression in kidney cortex, while PTMAP9 (Z = 1.16), RRAGA (Z = 1.37) and CREB1 (Z = 1.21) are most abundant in the aorta." (PMID 40909129, 2025).
internalizing disorder (1 paper, 2023). A type of mental or behavioral disorder, typically in children and young adults, with symptoms including depression, anxiety and withdrawal. "RRAGA, which regulates the mTOR signaling cascade that may have a role in the antidepressant effects of NMDA antagonists, was the most interacting gene associated with GAD, highlighting the possible role of the mTOR pathway for internalizing disorder treatment." (PMID 37216417, 2023).
Nail dystrophy (1 paper, 2020). Onychodystrophy (nail dystrophy) refers to nail changes apart from changes of the color (nail dyschromia) and involves partial or complete disruption of the various keratinous layers of the nail plate. "Among the top associations, we recapitulated previously known, such as "SRD5A3—Abnormal full-field electroretinogram—recessive" and "GRHL2 –Nail dystrophy—recessive", and discovered one potentially novel, “RRAGA–Abnormality of the skin—dominant”." (PMID 32271766, 2020).
nuclear cataract (1 paper, 2016). A cataract (disease) that involves the lens nucleus. "But mutation c.179T>G was found to be heterozygous both in a family and an unrelated simplex patient with juvenile onset posterior cataracts, and another RRAGA mutation, c.-16G>A, was found in a patient with bilateral congenital nuclear cataracts." (PMID 27294265, 2016). "In our study, RRAGA p.Leu60Arg that up-regulated mTORC1 is associated with juvenile onset posterior cataracts, while c.-16G>A that reduces promoter activity is associated with congenital nuclear cataracts." (PMID 27294265, 2016).
posterior subcapsular cataracts (1 paper, 2016). "In the current study, using WES, we identified a novel heterozygous missense p.Leu60Arg mutation in RRAGA that co-segregated with progressive juvenile-onset posterior subcapsular cataracts." (PMID 27294265, 2016).
prostate carcinoma (1 paper, 2020). A carcinoma that arises from epithelial cells of the prostate gland. "In prostate cancer, genetic alterations in RRAGA and RRAGC genes that encode RAGA and RAGC respectively are uncommon, however RRAGB (encoding RAGB) is amplified in up to 7.7% of cases and RRAGD (encoding RAGD) deep deletion occurs in 6.5–14.4% of cases." (PMID 32630372, 2020).
senile cataract (1 paper, 2016). A cataract with no obvious cause occurring in persons over 50 years old. "Given that senile cataracts are a common age-related disease, the progressive opacification of the crystalline lens in patients with RRAGA mutations might be considered as a phenotype of premature ageing that occurs specifically in the crystalline lens." (PMID 27294265, 2016).
type 1 diabetes (1 paper, 2025). "A more in-depth analysis of hub genes revealed that the expression of SMARCA4, a DE gene, and RRAGA, a protein interactor included during PPI-network construction, stratified progression to type 1 diabetes after seroconversion." (PMID 41306972, 2025).
cancer (9 papers, 2017 to 2025). A tumor composed of atypical neoplastic, often pleomorphic cells that invade other tissues. "In the Cancer Cell Line Encyclopedia (CCLE), expression of FNIP2 and RRAGD, and to some extent RRAGC, but not RRAGA or RRAGB, correlates with MITF expression." (PMID 41275493, 2025).
skin disorder (1 paper, 2020). Any deviation from the normal structure or function of the skin or subcutaneous tissue that is manifested by a characteristic set of symptoms and signs. "RRAGA encodes Ras-related GTP-binding protein A that activates mTORC, which was found to regulate skin morphogenesis and epidermal barrier formation, therefore its mutations are the possible pathogenic cause of the skin disorders observed on the patients in the Phenopolis dataset." (PMID 32271766, 2020).
RRAGA also shares sentences with these, for which no sentence is quoted: tumor (6 papers); colorectal cancer (2); depression (2); periodontal disease (2); acute myeloid leukaemia (1); Alzheimer disease (1); autism spectrum disorder (1); bacterial infection (1); cardiomyopathy (1); focal epilepsies (1); glioblastoma (1); hyperglycaemia (1); Juvenile onset (1); lung adenocarcinoma (1); lung carcinoma (1); memory impairment (1); mood disorder (1); neuroblastoma (1); neurological disorders (1); periodontitis (1); Venous thrombosis (1).